HGD (homogentisate 1,2-dioxygenase)
Description:
Catalyzes the conversion of homogentisate to maleylacetoacetate.
Synonyms: HGO; AKU
Tractability: PROTAC: its protein half-life has been measured.
Gene: Protein-coding gene on chromosome 3 (120,628,165 to 120,682,385, reverse strand). Ensembl gene ENSG00000113924.
Subcellular location (Human Protein Atlas): Golgi apparatus
Pathways (Reactome):
Metabolism: Tyrosine catabolism
Gene Ontology:
Molecular function: homogentisate 1,2-dioxygenase activity; identical protein binding; protein binding
Biological process: L-tyrosine catabolic process; L-phenylalanine catabolic process
Cellular component: extracellular exosome; cytosol
Genetic constraint (gnomAD): Loss-of-function variants: 42 observed, 45.31 expected, observed/expected ratio (o/e) 0.93, 90% interval 0.72 to 1.2. The upper end of that interval is the gene's LOEUF score, 1.2, which puts it in group 5 of 6, group 1 being the genes least tolerant of losing a copy. Missense variants: 446 observed, 478.57 expected, observed/expected ratio (o/e) 0.93, 90% interval 0.86 to 1.01. Synonymous variants: 176 observed, 164.69 expected, observed/expected ratio (o/e) 1.07, 90% interval 0.94 to 1.21.
Gene-disease validity (ClinGen):
ClinGen rates the evidence that HGD causes each of these diseases.
alkaptonuria (autosomal recessive): Definitive.
Homologues: Orthologues: chimpanzee HGD (99% identical), rabbit HGD (95% identical), dog HGD (94% identical), guinea pig HGD (93% identical), mouse Hgd (93% identical), pig HGD (92% identical), rat Hgd (91% identical), macaque HGD (90% identical), zebrafish hgd (79% identical), tropical clawed frog hgd (78% identical), Drosophila melanogaster hgo (66% identical), Caenorhabditis elegans hgo-1 (64% identical).
Diseases named in the same sentence as HGD in open-access papers:
HGD is named in the same sentence as 25 diseases in open-access papers, as found by Europe PMC text mining. Sharing a sentence is not in itself a finding about the gene and the disease. The quoted sentences say what the papers report.
alkaptonuria (70 papers, 2010 to 2026). "Alkaptonuria results from a deficiency of the enzyme HGD, leading to a block in the phenylalanine-tyrosine degradation pathway and subsequent accumulation of HGA." (PMID 41356868, 2025). "Alkaptonuria is a rare autosomal recessive metabolic disorder caused by mutations in the HGD gene, which encodes the enzyme homogentisate 1,2-dioxygenase (HGD)." (PMID 41356868, 2025). "Alkaptonuria is a rare metabolic disorder caused by a mutation in the homogentisate 1,2 dioxygenase (HGD) gene, which encodes the HGD enzyme." (PMID 40995248, 2025). "Alkaptonuria, a hereditary condition characterized by a deficiency of homogentisate 1,2 dioxygenase (HGD), results in the deposition of homogentisic acid (HGA) in various collagenous tissues throughout the body." (PMID 38978889, 2024). "Alkaptonuria is a rare autosomal recessive disease caused by a mutation in the homogentisate 1,2-dioxygenase (HGO) gene, leading to the accumulation of homogentisic acid (HGA)." (PMID 39027761, 2024). "Alkaptonuric ochronosis, characterized by the deposition of homogentisic acid in connective tissues, is commonly linked with alkaptonuria, a rare genetic disorder resulting from homogentisate 1,2-dioxygenase deficiency." (PMID 39399636, 2024). "Alkaptonuria is a rare autosomal recessive metabolic disorder that is caused by a mutation of the homogentisate 1,2-dioxygenase (HGD) gene, which leads to HGD deficiency, which in turn is part of the phenylalanine and tyrosine degradation processes." (PMID 39027761, 2024). "It is most often associated with alkaptonuria, an autosomal recessive disorder caused by a deficiency in homogentisate 1,2-dioxygenase, an enzyme crucial for breaking down homogentisic acid." (PMID 39399636, 2024). "Alkaptonuria results in the accumulation of homogentisic acid in connective tissues due to the deficiency of HGD enzyme." (PMID 37937039, 2023). "Alkaptonuria (AKU) is a rare debilitating autosomal recessive disorder of tyrosine (TYR) metabolism which results in a deficiency of the enzyme homogentisate 1,2‐dioxygenase activity." (PMID 35822095, 2022). "Metabolic disorder alkaptonuria is an autosomal recessive disorder caused by mutations in the HGD gene, and a deficiency HGD enzyme activity results in an accumulation of homogentisic acid (HGA), ochronosis, and destruction of connective tissue." (PMID 34235214, 2021). "Alkaptonuria is an autosomal recessive mutation resulting in a deficiency of homogentisate 1,2-dioxygenase (HGD) that leads to an accumulation of HGA." (PMID 33666743, 2021). "Ochronosis/alkaptonuria is an autosomal recessive mutation resulting in a deficiency of homogentisate 1,2-dioxygenase, leading to an accumulation of HGA." (PMID 33666743, 2021). "According to these results, dietary fat restriction should be considered to avoid adverse homogentisic acid (HGA) accumulation, for instance in alkaptonuria patients with residual HGD enzymatic activity caused by missense mutations in the HGD gene." (PMID 34063343, 2021). "Alkaptonuria (AKU) is caused by homogentisate 1,2‐dioxygenase deficiency that leads to homogentisic acid (HGA) accumulation, ochronosis and severe osteoarthropathy." (PMID 31503358, 2020). "Alkaptonuria, caused by a deficiency of homogentisate 1,2-dioxygenase, results in the accumulation of homogentisic acid (2,5-dihydroxyphenylacetic acid, HGA) in the urine." (PMID 24466168, 2014). "Alkaptonuria (AKU) is a rare autosomal recessive metabolic disorder due to a deficiency of homogentisate 1,2-dioxygenase, subsequently leading to the progressive acquisition of ochronosis, osteoarthropathy, systemic complications, and the pathological retention of homogentisic acid (HGA)." (PMID 41377225, 2025). "Here we present an empirical classifier, HGDiscovery, which has phenotypic information on all known variants of homogentisate 1,2 dioxygenase, (EC 1.13.11.5), an enzyme involved in the metabolism of tyrosine, whose deficiency leads to Alkaptonuria [OMIM 203500]." (PMID 36118553, 2022).
alkaptonuria (continued). "Alkaptonuria is an inherited disorder affecting this function, caused by non-functional and or suboptimal activity of the enzyme homogentisate 1,2-dioxygenase dioxygenase (HGD) (EC 1.13.11.5)." (PMID 29682508, 2018). "Alkaptonuria is often diagnosed clinically with episodes of dark urine, biochemically by the accumulation of peripheral homogentisic acid and molecularly by the presence of mutations in the homogentisate 1,2-dioxygenase gene (HGD)." (PMID 25233259, 2014). "One such condition is the inherited metabolic disorder alkaptonuria (AKU), caused by mutations in the gene encoding the homogentisate 1,2-dioxygenase (HGD) enzyme." (PMID 42184121, 2026). "Alkaptonuria (AKU) (OMIM #203500) is caused by mutations in HGD (OMIM 607474), leading to a homogentisic acid oxidase (EC 1.13.11.5) deficiency and consequent homogentisic acid (HGA) accumulation." (PMID 41464651, 2025). "Alkaptonuria (AKU) is a rare autosomal recessive inborn error of the tyrosine metabolism caused by the deficiency of homogentisic dioxygenase (HGD) resulting in the accumulation of homogentisic acid (HGA)." (PMID 39435171, 2024). "Alkaptonuria (AKU) is an exceptionally rare autosomal recessive genetic disorder caused by a deficiency in the enzyme homogentisate 1,2−dioxygenase (HGD)." (PMID 39351877, 2024). "Alkaptonuria (AKU) is a rare autosomal recessive metabolic disorder caused by mutations in the homogentisate 1,2-dioxygenase (HGD) gene, leading to the accumulation of homogentisic acid (HGA), causing severe inflammatory conditions." (PMID 39273071, 2024). "Alkaptonuria (AKU) is an inherited disease resulting from a deficiency of the enzyme homogentisate 1,2-dioxygenase which is characterized by severe cartilage degeneration, similar to that observed in OA." (PMID 35761830, 2022). "Alkaptonuria (AKU) is an ultra-rare autosomal recessive disease caused by a mutation in the homogentisate 1,2-dioxygenase gene." (PMID 39086980, 2022). "Alkaptonuria (AKU) is a rare autosomal recessive disorder caused by mutations within a gene coding for homogentisate 1,2-dioxygenase (HGD)." (PMID 36295892, 2022). "Alkaptonuria (AKU) is a rare inborn error of metabolism caused by a defective homogentisate 1,2-dioxygenase (HGD), an enzyme involved in the tyrosine degradation pathway." (PMID 36376482, 2022). "Alkaptonuria (AKU) is a rare inherited disease resulting from a deficiency of the enzyme homogentisate 1,2‐dioxygenase which leads to the accumulation of homogentisic acid (HGA)." (PMID 28158906, 2017). "Alkaptonuria (AKU) is an ultra-rare genetic disorder caused by mutations in the homogentisate 1,2-dioxygenase (HGD) gene, leading to the accumulation of homogentisic acid (HGA)." (PMID 40243989, 2025). "Alkaptonuria (AKU) is a rare autosomal recessive metabolic disorder caused by pathogenic variants in the homogentisate 1,2-dioxygenase (HGD) gene." (PMID 37658095, 2023). "Alkaptonuria (AKU; OMIM #203500) is a rare inherited metabolic bone disease caused by deficiency of homogentisate 1,2-dioxygenase (HGD; EC 1.13.11.5)." (PMID 33057760, 2021). "Alkaptonuria (AKU) is an ultra-rare autosomal recessive disease caused by a mutation in the homogentisate 1,2-dioxygenase (HGD) gene." (PMID 32050984, 2020). "Alkaptonuria (AKU) is an ultra‐rare metabolic disease in which a deficiency of the enzyme homogentisate 1,2‐dioxygenase leads to the accumulation of homogentisic acid (HGA) (La Du, Zannoni, Laster, & Seegmiller, 1958); for review see Gallagher, Dillon, Sireau, Timmis, and Ranganath (2016)." (PMID 28158906, 2017). "Alkaptonuria (AKU) is a disorder of phenylalanine/tyrosine metabolism due to a defect in the enzyme homogentisate 1,2-dioxygenase (HGD)." (PMID 26788390, 2015). "Alkaptonuria (AKU) is an inborn error of catabolism due to adeficient activity of homogentisate 1,2-dioxygenase." (PMID 25567001, 2014).
alkaptonuria (continued). "In this communication, we describe a novel 649 bp deletion that encompasses exon 2 of the HGD gene in a Lebanese individual, reported to have alkaptonuria and Pompe’s disease." (PMID 25233259, 2014). "Alkaptonuria (AKU; OMIM #203500), a rare autosomal recessive disorder resulting from mutations in the homogentisate 1,2-dioxygenase (HGD) gene, has a wide spectrum of clinical manifestations." (PMID 25233259, 2014). "Alkaptonuria (AKU) results from a deficiency of homogentisate-dioxygenase (HGD) that degrades homogentisic acid (HGA), an intermediary product of tyrosine catabolism." (PMID 22105303, 2012). "Alkaptonuria (AKU) results from defective homogentisate-dioxygenase (HGD), causing degenerative arthropathy." (PMID 22105303, 2012). "Alkaptonuria (AKU; OMIM 203500) is an autosomal-recessive monogenic metabolic disorder caused by pathogenic variants in the HGD gene, resulting in a deficiency of homogentisate 1,2-dioxygenase." (PMID 41226673, 2025). "Mutations in the HGD gene lead to an autosomal recessive disorder known as alkaptonuria, which is characterized by the absence of HGD causing an accumulation of HGA." (PMID 38422035, 2024). "As a control of a TIMD without hepatic manifestation, we used a homogentisate 1,2-dioxygenase (Hgd)-deficient mouse model of alkaptonuria (AKU, OMIM #203500) also under continuous NTBC treatment." (PMID 36980965, 2023). "Alkaptonuria (AKU) is an inherited disorder of tyrosine metabolism caused by lack of active enzyme homogentisate 1,2-dioxygenase (HGD)." (PMID 35685462, 2021). "In particular, Alkaptonuria (AKU) is an ultra-rare autosomal recessive metabolic disease with a very low prevalence (1:1,000,000–250,000), caused by mutation in the structure of homogentisate 1,2-dioxygenase (HGD), an enzyme involved in the metabolism of tyrosine and phenylalanine." (PMID 33530326, 2021). "Deleterious missense mutations analyses for the HGD gene causing alkaptonuria have not been estimated computationally till now by modelling approach, although they have received great focus from experimental researchers." (PMID 22606059, 2012). "Alkaptonuria (AKU, OMIM reference 203500) is a rare autosomal recessive disorder caused by a deficiency in homogentisate 1,2‐dioxygenase (HGD, EC 1.13.11.5), the third enzyme in the tyrosine catabolic pathway." (PMID 35028270, 2022). "Alkaptonuria (AKU), a rare genetic disorder, is characterized by the accumulation of homogentisic acid (HGA) in organs due to a deficiency in functional levels of the enzyme homogentisate 1,2-dioxygenase (HGD), required for the breakdown of HGA, because of mutations in the HGD gene." (PMID 34799606, 2021). "Alkaptonuria (AKU; OMIM #203500) is a rare metabolic recessive disease where the enzyme homogentisate 1,2-dioxygenase (HGD; EC 1.13.11.5), which is mainly found in the liver, is deficient." (PMID 31600782, 2019). "We found SAA amyloidosis as a life-threatening complication inalkaptonuria (AKU), an ultra-rare(1:250.000-1.000.000 incidence) autosomal recessive genetic disease due to adeficient activity of homogentisate 1,2-dioxygenase (HGD) leading to theaccumulation of homogentisic acid (HGA)." (PMID 25567001, 2014). "Ochronosis and alkaptonuria are manifestations of the same condition – a rare autosomal recessive disorder resulting from a constitutional lack of homogentisate 1,2-dioxygenase (HGD) with the consequent accumulation of homogentisic acid (HGA)." (PMID 33666743, 2021). "Alkaptonuria (AKU, OMIM: 203500) is a rare bi-allelic autosomal recessive disorder of the tyrosine metabolic pathway, occurring 1 in 100,000–250,000 of the general population and arises from a congenital deficiency in the enzyme homogentisate-1,2-dioxygenase (HGD, E.C.1.12.11.5)." (PMID 31037385, 2019).
alkaptonuria (continued). "Alkaptonuria is an inherited disorder of aromatic amino acid metabolism and results from absence of homogentisate 1,2 dioxygenase (HGD), the enzyme predominantly produced by hepatocytes in the liver and in the kidney, responsible for the breakdown of homogentisic acid (HGA)." (PMID 33407701, 2021). "Alkaptonuria (AKU) is an ultrarare and multifaceted disease characterized by the absence of functional homogentisate 1,2‐dioxygenase activity, the enzyme responsible for breakdown of homogentisic acid—a tyrosine‐degradation product." (PMID 32395411, 2020).
glioma (2 papers, 2023 to 2024). A benign or malignant brain and spinal cord tumor that arises from glial cells (astrocytes, oligodendrocytes, ependymal cells). "Highly expressed tyrosine metabolizing enzymes 4‐hydroxyphenylpyruvate dioxygenase, homogentisate 1,2‐dioxygenase, and fumarylacetoacetate hydrolase not only promote the malignant phenotype of glioma but are also closely related to poor prognosis." (PMID 37786553, 2023). "Third, in glioma, increased protein levels of the tyrosine degradation pathway (HPD, HGD, and FAH) was correlated with higher PD-L1 expression, which promoted immune evasion by suppressing T-cell activity." (PMID 39592957, 2024). "In all, the highly expressed HPD, HGD, and FAH in glioma modulate the TME, alter the abundance of immune cells, and promote immune evasion." (PMID 37786553, 2023). "In the CGGA database, the expressions of HPD, HGD, and FAH were significantly elevated in high‐grade glioma and IDH wild‐type glioma." (PMID 37786553, 2023). "Taken together, these results suggest that the tyrosine metabolizing enzymes HPD, HGD, and FAH promote the malignant phenotype of glioma, which in turn exacerbates the poor prognosis of patients." (PMID 37786553, 2023). "To clarify the specific mechanism of tyrosine metabolizing enzymes regulating the malignant phenotype of glioma, we first calculated the optimal “cutpoint” using the R package algorithm and divided glioma patients into two groups according to the expression levels of HPD, HGD, and FAH." (PMID 37786553, 2023). "In addition, abnormal expression of tyrosine metabolizing enzymes (HPD, HGD, and FAH) alters the TME of glioma." (PMID 37786553, 2023).
hepatocellular carcinoma (2 papers, 2021 to 2022). A malignant tumor that arises from hepatocytes. "Our previous work found that decreased tyrosine metabolism promotes cell cycle in hepatocellular carcinoma, and we found that down-regulation of HGD and GSTZ1 also promotes cell cycle in KIRC." (PMID 35562974, 2022). "The downregulation of tyrosine metabolism pathway-related genes (HPD, HGD, GSTZ1, and FAH) was observed in hepatocellular carcinoma and indicated poor prognosis; however, investigation of dysregulation of tyrosine metabolism pathways in OSCC is lacking." (PMID 34422810, 2021).
renal carcinoma (2 papers, 2022 to 2023). A carcinoma arising from the epithelium of the renal parenchyma or the renal pelvis. "Therefore, we found that the HGD/GSTZ1-GOT1/GOT2 axis drives renal cancer cells to undergo aerobic glycolysis, converting uptake glucose into lactate to obtain energy to meet their own needs." (PMID 35562974, 2022). "We believe that the tyrosine metabolizing enzymes HGD and GSTZ1 are reliable biomarkers of KIRC, which will provide important help for the clinical diagnosis and treatment of renal cancer." (PMID 35562974, 2022). "Mechanistically, we found that decreased HGD and GSTZ1 regulate amino acid metabolism to reduce fumarate production, which in turn remodels metabolic flux and energy production in renal cancer cells, ultimately promoting cell cycle and proliferation." (PMID 35562974, 2022). "At the molecular level, we found that SLC2A1, LDHA, GOT1, and GOT2 were regulated by HGD and GSTZ1 to alter the glucose uptake and energy metabolism of renal cancer cells." (PMID 35562974, 2022). "Wang J and his research team illustrated that two enzymes involved in tyrosine metabolism, homogentisate 1,2-dioxygenase (HGD), and glutathione S-transferase zeta 1 (GSTZ1) were downregulated in three renal cancer types (KIRC, KIRP, and KICH) of tissues versus healthy ones." (PMID 37176098, 2023). "However, the mutation rate of HGD and GSTZ1 was only 0.7% in KIRC, indicating that the function of HGD and GSTZ1 in renal cancer depends on the expression abundance." (PMID 35562974, 2022).
tyrosinemia (2 papers, 2013 to 2022). An autosomal recessive inherited metabolic disorder caused by mutations in the FAH, HPD, and TAT genes. "They utilized Fah-deficient mice (Fah−/−) with tyrosinemia-related liver injury and mice heterozygous for a mutation in the homogentisate 1,2-dioxygenase (Hgd) gene (Hgd+/−)." (PMID 36012671, 2022). "Chromosome 16 carries the homogentisic acid dioxygenase (HGD) gene and loss of HGD in a heterozygous background causes resistance to tyrosinemia-induced hepatic injury." (PMID 23760367, 2013).
cholangiocarcinoma (1 paper, 2021). A carcinoma that arises from the intrahepatic biliary tree (intrahepatic cholangiocarcinoma) or from the junction, or adjacent to the junction, of the right and left hepatic ducts (hilar cholangiocarcinoma). "The downregulation of HGD expression was found to be associated with less metastasis, as well as better prognosis, pathological grade, and clinical stage of cholangiocarcinoma patients." (PMID 34796198, 2021).
clear cell renal carcinoma (1 paper, 2024). A malignant epithelial neoplasm of the kidney characterized by the presence of lipid-containing clear cells within a vascular network. "Moreover, a decrease in HGD activity could potentially result in decreased malate levels, thereby impacting the tricarboxylic cycle, oxidative phosphorylation, as well as amino acid and glucose metabolism, as suggested for clear cell renal carcinoma." (PMID 38422035, 2024).
kidney stones (1 paper, 2024). "Mutations in homogentisate 1,2-dioxygenase can cause its accumulation, resulting in dark urine, cartilage damage, kidney stones, and heart valve issues." (PMID 38540220, 2024).
liver cancer (1 paper, 2022). An epithelial or non-epithelial malignant neoplasm that arises from the liver. "Previous studies also showed that genes from tyrosine metabolism reprogramming (TAT, HPD, HGD, GSTZ1, and FAH) may be used as prognostic biomarkers in liver cancer." (PMID 35847355, 2022).